ISG15 (ISG15 ubiquitin like modifier)
Diseases named in the same sentence as ISG15 in open-access papers (continued):
Sharing a sentence is not in itself a finding about the gene and the disease.
breast cancer (68 papers, 2008 to 2026). A primary or metastatic malignant neoplasm involving the breast. "ISG15 has been reported to be aberrantly overexpressed in various malignant tumors, including high-grade serous ovarian cancer, cervical cancer, breast cancer, and prostate cancer, and is associated with poor prognosis." (PMID 40208307, 2025). "With the aid of spatial transcriptomics and proteomics data, we confirmed that ISG15 is highly expressed and predominantly co-located with the myCAF subcluster in breast cancer, underlining its significant role in pro-tumor." (PMID 40904511, 2025). "Beyond diagnosis, ISG15’s association with various cancers, such as breast cancer and pancreatic cancer, provides insight into DM’s link with malignancies." (PMID 39559355, 2024). "ISG15-mediated fork protection is beneficial to cancer cells; indeed, the sole upregulation of ISG15 increases resistance of BRCA2-deficient mouse breast cancer cells to platinum-derived chemotherapeutic agents." (PMID 37783689, 2023). "The conjugated ISG15 (ISGylation) has pro-tumorigenic activity, while the extracellular free form has anti-tumorigenic activity in breast cancer and is being considered as a tumor-associated antigen for cancer immunotherapy." (PMID 37245006, 2023). "Inhibition of this loop by silencing either Ki-Ras or the ISG15 pathway restored the disrupted cellular architecture of breast cancer cells, which is a hallmark of most cancer cells." (PMID 35159348, 2022). "ISG15 is an ubiquitin-like modifier that is associated with reduced survival rates in breast cancer patients." (PMID 34556814, 2021). "PCLAF and ISG15 overexpression are associated with poor prognosis of breast cancer, and DTL knockdown decreases breast cancer cells’ proliferation and metastasis." (PMID 33662042, 2021). "In breast cancer, expression of an immune response gene subgroup, which includes ISG15, MX1, and other interferon genes, has been associated with improved prognosis in triple negative breast cancers." (PMID 30253781, 2018). "(H) DTX3L mRNA expression is positively associated with ISG15 expression in human basal-like breast cancers." (PMID 29350614, 2018). "In tubular breast carcinomas, a less frequent variant of invasive breast carcinomas with a more favourable prognosis than invasive ductal breast carcinomas, ISG15 expression was less abundant than in most invasive ductal breast carcinomas." (PMID 18627608, 2008). "In the initial TMA cohort, ISG15 protein expression in breast carcinomas (IRS > 4) was associated with the ER status (p = 0.028), but not with tumour size, lymph node status, histological grading, focality or histological type of tumour." (PMID 18627608, 2008). "Higher ISG15 expression was also associated with poor prognosis in breast cancer." (PMID 36077244, 2022). "These include genes such as PAEP, which encodes the protein glycodelin, a lipocalin protein associated with reproductive cancers including breast cancer, ISG15, a prognostic marker in breast cancer, and ANKRD1, which has been associated with lung and ovarian cancer." (PMID 34681087, 2021). "However, ISG15 was found to be overexpressed in breast carcinoma, and ISG15 overexpression was associated with an unfavourable prognosis." (PMID 31949544, 2019). "Jeon and associated showed that ISG15 played a role in the down-regulation of ΔNp63α in human breast cancer cells, suggesting that ISGylation may play a role in suppressing oncogenesis." (PMID 30469497, 2018). "As a next step we will investigate whether an ISG15-based diagnostic assay is able to predict response to specific chemotherapy regimens in the treatment of breast cancer." (PMID 18627608, 2008). "Our proteomics cohort (in-house cohort) indicated a substantial upregulation of ISG15 expression in breast cancer tissues compared to normal tissues, a finding supported by paired comparisons in the GSE109169 cohort." (PMID 40904511, 2025).
breast cancer (continued). "High levels of ISG15 expression are associated with resistance to radiation therapy and confer resistance to cisplatin in BRCA2-deficient breast cancer cells." (PMID 40103488, 2025). "In summary, our study indicated that ISG15 was significantly upregulated in breast cancer, however, its functional role in TNBC specimens with BRCA1 mutation remained elusive." (PMID 40904511, 2025). "It was also shown to be part of an IFN-related DNA damage resistance signature in breast cancer, together with ISG15, another gene in the signature." (PMID 40312750, 2025). "Most prior research on the UBA7/ISG15 signaling pathway in cancer has concentrated on lung and breast cancer and reported that UBA7 gene expression was downregulated." (PMID 40158006, 2025). "Pertaining to breast cancer and colon cancer, ISG15 expression levels correlate with RFS (breast cancer: RFS, HR = 1.36, log-rank P = 2.9e−07; colon cancer: RFS, HR = 1.5, log-rank P = 0.0031)." (PMID 40208307, 2025). "MCF7 and T47D cells derived from breast cancer showed weak induction of ISG15 expression and protein ISGylation conjugates formation, even though protein ISGylation conjugates were present even in the absence of doxorubicin." (PMID 38443596, 2024). "We also used a single sample gene set enrichment analysis (ssGSEA) algorithm to establish an ‘ISG15+ Tregs’ signature and found that the ISG15+ Tregs activity scores in BCBrM tissues were significantly higher than that in paired primary breast cancer tissues." (PMID 38943472, 2024). "ST_7 showed higher gene expression of interferon (IFN)‐inducible genes such as ISG15, IFIT1 and IFI6, which were recently demonstrated to be associated with ER+ breast cancer therapy resistance." (PMID 38282415, 2024). "UBE2E2 has been shown to promote cancer cell movement and invasion in breast cancer cells through its action on ISG15." (PMID 39057719, 2024). "Nevertheless, ISG15 enhances the stability of Ki-Ras, inhibiting its lysosomal degradation in breast cancer cells." (PMID 37711589, 2023). "Oncogenic Ki-Ras regulates the expression of ISG15 and ISGylation, which in turn stabilizes Ki-Ras by inhibiting its degradation through lysosomes in breast cancer cells, suggesting that the ISGylation pathway is a key downstream mediator of oncogenic Ki-Ras." (PMID 36771004, 2023). "We have identified four mouse myeloid subpopulations that highly correlate with breast cancer metastasis to lung, including Tppp3+ monocytes, Isg15+ macrophages, Ifit3+ neutrophils, and Il12b+ DCs." (PMID 37483625, 2023). "Some studies have shown that the depletion of ISG15 expression reduces the proliferation and migration of breast carcinoma-derived cells." (PMID 37711589, 2023). "Other studies have shown overexpression of ISG15 at either the mRNA or the protein level, which was related to the poor prognosis of breast cancer patients." (PMID 35116193, 2022). "ISG15 is known to disrupt the F-actin cytoskeletal structure and focal adhesions as well as promote motility in human ZR-75-1 breast cancer cells." (PMID 35328492, 2022). "Concurrently, it has been reported that the ISG15 pathway (ISG15 and its conjugating enzymes) is overexpressed in human breast cancer cells and clinical specimens and inhibits protein degradation in cancer cells." (PMID 35159348, 2022). "Because the cellular architecture is conserved and the ISG15 pathway is constitutively activated in a variety of tumors, it is reasonable to assume that the breast cancer observations must hold true for many other tumors." (PMID 35159348, 2022). "Upregulation of ISG15 and ISGylated proteins in primary tumor cells derived from breast cancer patients has been reported." (PMID 36319753, 2022). "ISG15 upregulation in breast cancer correlates with not only poor response to chemotherapy and radiotherapy but also subsequent unfavorable prognosis." (PMID 36319753, 2022).
breast cancer (continued). "IFNγ upregulates ISG15 and promotes ISGylation in breast cancer cells, which occurs in parallel with changes in the morphology of breast cancer cells." (PMID 36319753, 2022). "ISG15 drives chemotherapy and radiation resistance of breast cancer cells in a process involving paracrine and juxtacrine communications between stroma and breast cancer cells." (PMID 36319753, 2022). "Some researchers reported that downregulation of ISG15 increased the camptothecin resistance in breast cancer, while another study showed that high ISG15 expression in breast cancer indicated radiation resistance and poor prognosis." (PMID 33791224, 2021). "In this study, we aimed to identify the molecular mechanisms that explains why high ISG15/ISGylation correlates with poor patient prognosis in breast cancer." (PMID 34556814, 2021). "We further show that Akt signalling positively correlates with levels of ISG15 and its E2-ligase in basal breast cancer cohorts, confirming the link between ISGylation and Akt signalling in human tumours." (PMID 34556814, 2021). "Tumour progression and aggressiveness of several cancer types, including endometrium, bladder, prostate, melanoma, colorectal, liver and breast cancer has been correlated to ISG15 expression." (PMID 34556814, 2021). "Currently, numerous studies have reported that ISG15 is involved in various tumors, such as breast cancer, oral squamous cell carcinoma, pancreatic cancer, and endometrioid endometrial adenocarcinoma." (PMID 34696780, 2021). "In breast cancer cells, enhanced ISG15 expression is induced through exosome-mediated cGAS activation and from nuclear DNA release after DNA damage." (PMID 34556814, 2021). "Six hub genes, including IFIT1, ISG15, IFI6, GOLM5, KLHL35, and OAS2, were associated with the total survival probability in breast cancer patients." (PMID 30646630, 2019). "For example, aberrant overexpression of ISG15 has been shown to promote breast cancer cell invasion and tumorigenicity by disrupting cytoskeletal architecture, promoting cellular motility and enhancing the oncogenic function of Ki-Ras." (PMID 29350614, 2018). "High levels of ISG15 and its conjugates have been found in many types of primary tumors, including bladder, prostate, oral, and breast cancers." (PMID 30469497, 2018). "(D) ISG15 mRNA expression is positively correlated with LIPG expression in human basal-like breast cancers." (PMID 29350614, 2018). "A previous study evaluated the effects of silencing either ISG15 or UBE2L6 on drug sensitivity in breast cancer cells." (PMID 28186990, 2017). "Recent studies have revealed that intracellular free ISG15 promotes tumorigenesis and metastasis of hepatocellular cancer and breast cancer." (PMID 26919245, 2016). "Over-expression of ISG15 is involved in tumorigenesis and metastasis of various cancers, such as hepatocellular carcinoma, ovarian serous carcinoma, and breast cancer." (PMID 27888627, 2016). "So far it is clear that ISG15 overexpression is crucial in modulating cell growth and in the progression of breast cancer." (PMID 27626177, 2016). "While Burks and colleagues have demonstrated extracellular free ISG15 triggers an antitumor immune response and suppresses breast cancer growth." (PMID 26919245, 2016). "The high expression level of ISG15 has a significant correlation with unfavorable prognosis in esophageal squamous cell cancers and breast cancer." (PMID 27888627, 2016). "Although it has been proposed in carcinogenesis involved in several types of cancers, including lung cancer, breast cancer, and others, our present study suggests that ISG15 displays anti-cancer activity by disrupting the NF- κB signaling pathway." (PMID 27659523, 2016). "Recent studies from our group revealed that ISG15 inhibits polyubiquitylation, consequently inhibiting subsequent degradation of specific cellular proteins in breast cancer cells." (PMID 25749047, 2015).
breast cancer (continued). "We therefore assessed MHC class I surface expression on the MDA/LV-control shRNA breast cancer cells constitutively overexpressing ISG15 and MDA/LV-ISG15 shRNA cells silenced for ISG15 expression by the flow cytometry." (PMID 25749047, 2015). "We have demonstrated that ISG15 stabilizes key cellular proteins involved in cell migration/metastasis, conferring increased motility to breast cancer cells and promotes breast cell transformation." (PMID 25749047, 2015). "It was reported that ISG15 was highly expressed in multiple human cancer cell lines, and ISG15 plays crucial roles in modulating cell growth and progression of breast cancer." (PMID 25238261, 2014). "Mounting studies have identified specific alterations of ISG15 pathway in human tumors, such as bladder cancer, prostate cancer, breast cancer, colorectal cancer, and acute multiple sclerosis lesions." (PMID 25238261, 2014). "ISG15 is variably expressed in three breast cancer cell lines, with ISG15 expression being the highest in ZR-75-1 as compared to BT474 and T47D." (PMID 21897875, 2011). "Our current studies have suggested that the increased secretion of IFN-β with subsequent activation of the type I IFN signaling pathway is responsible for ISG15 overexpression in breast cancer ZR-75-1 cells." (PMID 21897875, 2011). "In the aggregate, these results suggest that ISG15 overexpression in ZR-75-1 breast cancer cells is due to elevated IFN-β signaling." (PMID 21897875, 2011). "Next we analysed ISG15 mRNA expression in primary breast cancers (n = 25) and normal mammary samples (n = 14) derived from formalin-fixed, paraffin-embedded tissues by real-time PCR." (PMID 18627608, 2008). "To the best of our knowledge, in the current study we present for the first time a systematic characterisation of ISG15 expression in human breast cancer and normal breast tissue both at the mRNA and protein level." (PMID 18627608, 2008). "ISG15 mRNA expression was also found to be upregulated after treatment of human colorectal and breast cancer cell lines with campothecin, a topoisomerase I inhibitor." (PMID 18627608, 2008). "In line with our breast cell line data, ISG15 mRNA was abundantly expressed in primary breast cancer specimens when compared with normal mammary epithelial tissue." (PMID 18627608, 2008). "Two independent cohorts of breast cancer specimens arranged on two different TMAs were analysed for ISG15 expression by immunohistochemistry." (PMID 18627608, 2008). "ISG15 mRNA was significantly upregulated in breast cancer specimens when compared with the corresponding normal breast tissues (p = 0.003, Mann-Whitney U-test)." (PMID 18627608, 2008). "In the initial cohort of breast carcinomas (n = 179) we found a significant correlation between ISG15 expression and unfavourable prognosis (RFS; p = 0.012) suggesting a potential role of ISG15 in breast cancer development." (PMID 18627608, 2008). "We found that ISG15 expression in breast cancer (IRS > 4) showed an unfavourable prognosis with regard to RFS as shown by Kaplan-Meier analysis (p = 0.012)." (PMID 18627608, 2008). "In breast cancer, ISG15 expression has so far only been examined in benign and malignant human breast cell lines." (PMID 18627608, 2008). "In accordance with previous findings in human cancer tissue we found upregulation of ISG15 at the mRNA level in breast carcinomas compared with normal breast tissue." (PMID 18627608, 2008). "ISG15 was overexpressed in breast carcinoma cells compared with normal breast tissue, both at the RNA and protein level." (PMID 18627608, 2008). "The interferon-stimulated gene 15 (ISG15) is a crucial therapeutic target for active tuberculosis and other comorbidities such as dermatomyositis, glioblastoma, psoriasis, hypertension, lung cancer, and breast cancer." (PMID 39024368, 2024).
breast cancer (continued). "We first assessed the expression of ISG15 and FOXP3 in breast cancer samples using the bc‐GenExMiner database, and we found a strongly positive correlation between ISG15 and FOXP3, indicating that ISG15 might be co‐expressing with FOXP3." (PMID 38943472, 2024). "ISG15 contributes to rat sarcoma virus protein-induced oncogenic transformation of breast epithelial cells and disrupts F-actin architecture and focal adhesion formation to promote migration of breast cancer cells." (PMID 39159817, 2024). "Current studies have shown that ISG15 could promote or inhibit cancer progression in different cancers; for example, free ISG15 can regulate immunity and promote NK cell infiltration, thus promoting breast cancer growth." (PMID 36771004, 2023). "ISG15 expression exhibits heterogeneity in tumors; in addition to a small number of cancers, ISG15 expression is obviously upregulated in a large number of tumors, such as bladder cancer, breast cancer, and ovarian cancer." (PMID 36771004, 2023). "In addition, when ISGylation levels are decreased by reducing the expression of ISG15, ubiquitination detection is enhanced in breast cancer cells." (PMID 37711589, 2023). "In addition, our analysis identified an IFN-responsive neutrophil population with high expression of IFN-responsive genes (Ifit3, Ifit1, Ifit3b, Ifi47, Ifitm3, Rsad2, Isg15, and Isg20), which is more present in metastatic lung of breast cancer." (PMID 37483625, 2023). "ISG15 depletion significantly reduces cell proliferation rates in human BRCA1-mutated triple-negative, whereas its upregulation results in increased resistance to the chemotherapeutic drug cisplatin in mouse BRCA2-deficient breast cancer cells, respectively." (PMID 37783689, 2023). "ISG15 impairs cytoskeleton architecture and the formation of focal adhesion in breast cancer cells." (PMID 36319753, 2022). "It has been demonstrated that free ISG15 inhibits tumor growth when added extracellularly and induces the infiltration of NK cells in tumors grown in nude mice, and intracellular free ISG15 enhances 26S proteasome-dependent surface expression of MHC Class I complexes on breast cancer cells." (PMID 35159348, 2022). "Treatment with ISG15 peptides suppresses primary and metastatic mammary tumor burden in mice." (PMID 36319753, 2022). "ISG15 downregulation decreases the sensitivity of breast cancer cells to camptothecin." (PMID 36319753, 2022). "IFNγ-induced ISG15 might affect the response of breast cancer cells to endocrine therapy with fulvestrant or tamoxifen." (PMID 36319753, 2022). "Interestingly, paradoxical role of ISG15 has been assigned to breast cancer, as free ISG15 plays a antitumour role by activating immune system in vivo in breast cancer, while the conjugated ISG15 triggers a malignant transformation of breast cells." (PMID 33797839, 2021). "Intracellular ISG15 has been shown to promote the expression of MHC class I complexes in breast cancer cells, while secreted ISG15 has been shown to exhibit anti-tumor activities by inducing NK cell proliferation and migration towards tumor cells and the release of IFN-γ from lymphocytes." (PMID 33718235, 2021). "Besides, ISG15 is a member of IFN-related DNA damage resistance signature in breast cancer and it is related to chemotherapy resistance, suggesting that high expression of ISG15 is a result of chronic activation of IFN signaling." (PMID 33330048, 2020). "ISG15 can disrupt cytoskeletal architecture and promote motility in human breast cancer cells." (PMID 32872349, 2020). "We noticed that a basal level of ISG15 protein expression was detectable in parental MCF7 cells, suggesting that there is a LIPG-independent mechanism for sustaining ISG15 expression in LIPG-deficient luminal breast cancer cells." (PMID 29350614, 2018).